EGFR (epidermal growth factor receptor)
Diseases named in the same sentence as EGFR in open-access papers (continued):
Sharing a sentence is not in itself a finding about the gene and the disease.
cancer (continued). "An emerging consensus is that α6β4 complex synergizes with specific molecules such as ErbB2, EGFR, Ron, Fyn, c-Met, protein kinase C, CD151, and CD9 to activate key signaling pathways for the invasion and migration of carcinoma cells via activation of signaling molecules such as PI3K." (PMID 24015244, 2013). "A peptide encoding EGFR 645–662 conjugated to the Tat sequence (TE-64562) displayed anti-cancer activity in multiple human cancer cell types with diminished activity in non-EGFR expressing cells and non-cancerous cells." (PMID 23166750, 2012). "The small interfering RNA-mediated knock-down of NEU3 in cancer cell lines, but not in normal cell-derived primary cultures, downregulates EGFR signaling and induces apoptosis." (PMID 22815940, 2012). "However, resistance to EGFR inhibitors often occurs, such as with KRAS mutant cancers, therefore new methods of targeting EGFR are needed." (PMID 23166750, 2012). "Recently, two related papers demonstrated that nuclear EGFR confers acquired resistance to an EGFR-TKI, gefitinib, by increasing the expression of breast cancer-resistant protein (BCRP), which is an ATP-binding cassette transporter that pumps anti-cancer drugs out of cells." (PMID 22520625, 2012). "Likewise, the phosphorylation of both EGFR and Akt and ERK1/2 were observed in cancer cell aggregates in ascites." (PMID 23046546, 2012). "It is now clear that NHERF1 promotes dimerization and activation of many tyrosine kinase receptors, such as the platelet derived growth factor receptor, the epidermal growth factor receptor and the HER2, known to directly regulate cell pathways related to cancer progression." (PMID 22439624, 2012). "Many of these genes play important roles in a central pathway (the EGF/EGFR/JAK1/AKT/NF-κB axis) that might lead to the survival and proliferation of cancer cells." (PMID 22479575, 2012). "We studied 39 consecutive NSCLC patients and measured the expression of six molecular markers (MDR-1, LRP, RRM-1, EGFR, ERCC-1, BRCA-1) in their primary tumors and metastatic lymph nodes and four well-known serum markers for cancer (NSE, CEA, CA-125, CYFRA 21-1)." (PMID 22890830, 2012). "TE-64562 displayed activity against growth in soft agar of several cancer cell lines which are EGFR positive (MDA-MB-231, A-549, DLD-1, MIA-PaCa-2) but no activity against growth of the EGFR-null SK-N-MC cell line." (PMID 23166750, 2012). "Some reports describe a dramatic increase in EGFR expression with progression of a dysplastic lesion to cancer without significant differences among various grades of dysplasia." (PMID 22322523, 2012). "Most cancer cell lines showed an EC50 in the range of 6 to 13 μM and expressed some level of EGFR." (PMID 23166750, 2012). "In the future, HER3-specific Affibody molecules may be useful in treatment of cancers where the HER3/HRG signalling is involved, potentially in combination with EGFR or HER2-targeted therapies." (PMID 22768204, 2012). "Recent evidence from both basic and clinical studies suggests that ERBB3 (HER3) serves as a key activator of downstream signaling through dimerization with other ERBB proteins and plays a critical role in the widespread clinical resistance to EGFR and HER2 targeting cancer therapies." (PMID 23342251, 2012). "In 19 of 53 primary tumors expressing EGFR, the corresponding metastatic site was found to be negative, whereas it was found to be positive in 15% metastases from EGFR-negative primary cancers." (PMID 23443093, 2012). "When adding CD44v6 to the panel, 80.1% of all cancers could be ‘detected’ with at least one marker in a panel consisting of HER2, GLUT1, EGFR, IGF1-R, and CD44v6." (PMID 22695343, 2012). "Recent progress in the development of molecular cancer therapy has revealed new molecular-targeting drugs, such as EGFR-targeting drug ZD1839 (Iressa) and HER2-targeting anti-HER2 monoclonal antibody trastuzumab (Herceptin), to be potent therapies for specific cancers." (PMID 22591714, 2012).
cancer (continued). "EGFR signaling pathways are upregulated in the majority of HNSCC tumors and are associated with a poor clinical prognosis as these cancers express an aggressive phenotype compared to EGFR negative cancers." (PMID 23118946, 2012). "Further, naturally occurring changes in EGFR trafficking often do not really manifest themselves (i.e., cancer) until later in life." (PMID 23344022, 2012). "Two EGFR family receptor members, namely EGFR itself and HER2, have been amongst the most extensively studied targets for the therapy of cancer over the past twenty years and a wealth of drugs directed against them have been either already approved or are in advanced clinical development." (PMID 22889873, 2012). "One of these patients had 4 foci, 2 of which were BLBCs while the other two were TN carcinomas without expression of basal keratins, EGFR or vimentin." (PMID 23082819, 2012). "Negative PTEN expression more frequently occurred in carcinomas overexpressing EGFR protein (14 out of 49, 28.6%) than in those without EGFR overexpression (35 out of 188, 18.6%), although not reaching statistical significance (P=0.164)." (PMID 22240798, 2012). "Some cancer cells carrying BRAF mutations are highly sensitive to MEK inhibitors, while cells lacking these BRAF mutations or containing RAS or epidermal growth factor receptor (EGFR) mutations are resistant." (PMID 21411864, 2011). "Therefore, several novel agents have been, or are currently being evaluated, including drugs targeted against the epidermal growth factor receptor (EGFR), vascular endothelial growth factor (VEGF) and different kinases involved in cancer proliferation." (PMID 21970874, 2011). "We hypothesised that cancer-associated fibroblasts (CAF) secrete NRG-1 ligand, which in turn activates cancer cell ErbB3/AKT-mediated signalling, promoting tumourigenesis and rendering EGFR inhibition ineffective." (PMID 21792199, 2011). "Altered expressions of EGFR and VEGF are early steps in the development of many cancers." (PMID 22214225, 2011). "Therefore, it is formally possible that an EGFR-mediated proliferative response involving overexpression of the MUC1-C subunit has been appropriated and subverted by cancer cells to promote their own growth and survival." (PMID 22140559, 2011). "In summary, our systems biology modeling reveals that there is a stronger apoptotic potential existing in the EGFR-addicted cancers, which is largely suppressed by the negative crosstalk between PI3K/AKT and ASK1/p38 signaling pathways." (PMID 22194952, 2011). "Increased EGFR expression and elevated TGF-α collectively promote autonomous growth (cellular growth in the absence of stimulating growth factors), a hallmark of cancer." (PMID 21949687, 2011). "However, only 10 different antigens are currently being targeted by mAbs developed for cancer therapies: EpCAM, MUC1, EGFR, CD20, CEA, HER2, CD22, CD33, Lewis Y and PSMA." (PMID 24212823, 2011). "The epidermal growth factor receptor (EGFR) is an important determinant of radioresponse, the elevated expression and activity of which frequently correlates with radioresistance in several cancers, including non-small-cell lung carcinoma (NSCLC)." (PMID 22104217, 2011). "Transactivation of EGFR is an important part of cancer progression, although the process is complex and as yet not fully understood." (PMID 22087246, 2011). "Both EGFR and PTGS2 (COX-2) represent promising targets for cancer prevention and treatment." (PMID 24213116, 2011). "Although cancer cells harboring amplified MET are initially sensitive to MET TKIs in vitro, they evade this inhibition, despite durable MET inhibition, via reactivation of EGFR and downstream mediators." (PMID 20628489, 2010). "Epidermal growth factor receptor (EGFR), p16 (CDKN2A), and cyclin D1 (CCND1), which may play an important role in the tumorigenesis and progression of this cancer, are located on chromosomes 7, 9, and 11, respectively." (PMID 20459605, 2010).
cancer (continued). "Recent studies indicated that Non-small cell lung cancer (NSCLC) patients with mutant K-RAS failed to benefit from adjuvant chemotherapy, and the cancer did not respond to epidermal growth factor receptor (EGFR) tyrosine kinase inhibitors (TKIs)." (PMID 20681447, 2010). "Nielsen and colleagues considered that lack of ER and HER2 and presence of epidermal growth factor receptor (HER1) and CK5/6 could identify basal-like carcinomas." (PMID 20678196, 2010). "Considering that these nucleotide synthesis-related genes are major determinants of fluoropyrimidine sensitivity, the dual inhibition of EGFR and HER2 TK by lapatinib appears to represent a promising strategy for the sensitization of cancer cells to fluoropyrimidines in a subset of tumors." (PMID 19529774, 2009). "Even though the majority of SCCHN cancers overexpress EGFR, these tumors are not solely dependent upon EGFR activity." (PMID 19636423, 2009). "The only classifier that performs reasonably well, with AUC = 0.78, is based on EGFR features selected manually with emphasis on sites observed frequently (without consideration of cancer subtype)." (PMID 19946374, 2009). "To assess the validity of this corrective algorithm, we applied the proposed normalization method to the quantification of EGFR, HER2 and HER3 in samples with decreasing RNA integrity obtained from two model-independent cancer cell lines (LS174T, colon; SKBr3, breast)." (PMID 19368728, 2009). "We have shown that a glycosylphosphatidylinositol (GPI)-anchored epithelial extracellular membrane serine protease, prostasin/PRSS8, modulates EGFR signalling via enhancement of matriptase cleavage of the EGFR extracellular domain (ECD), and regulates SLUG and E-cadherin expression in cancer cells." (PMID 19849847, 2009). "This involvement in cancer progression and a negative prognosis makes EGFR an attractive target for molecule therapy." (PMID 19178753, 2009). "Surface functionalizing GNPs by conjugation with a specific antibody, e.g., anti-epidermal growth factor receptor (EGFR) for epithelial cancer cells, has been developed for the application of these particles in the diagnosis and thermo-phototherapy of cancer cells." (PMID 27873891, 2008). "This could account for the inhibitory effects of EGCG on the autophosphorylation of the EGFR, HER2, and HER3 receptors in various types of cancer cells." (PMID 19325845, 2008). "Given the relative high inhibitory potency of MdOS against HER-2, EGFR and VEGFR2, together with the fact that HER-2, EGFR and VEGFR2 are the most verified targets in cancer therapy, we took these three kinases as representatives to probe MdOS -driven PTKs-associated events." (PMID 19020661, 2008). "It is unique in that, unlike mAbs which target the EGFR, it is only active against cancers that overexpress its target, therefore erbB2 testing prior to treatment is mandatory." (PMID 18991714, 2008). "Currently none of the aspects of EGFR status examined here has proven to be informative in predicting response to treatment with these monoclonal antibodies in other cancers." (PMID 18182111, 2008). "The results of this study support the idea that not only EGFR and VEGF but also Id-1 could be new targets in cancer treatment." (PMID 19014499, 2008). "The study indicated that a mediation model could be an approach to exploring the correlation pattern of EGFR and AKT signal pathway for cancer cell proliferation in OS patients in clinical study." (PMID 19662227, 2007). "Gefitinib monotherapy did not affect the PBDC nor the MSCfrequencies in the blood of the studied cancer patients (data not shown),consistent with the observed lack of EGFR expression on these cell populations." (PMID 18320010, 2007). "These novel genetic changes are either in known cancer genes (EGFR), result in a frameshift (FCGBP) or are rendered “not tolerated” by gene prediction algorithms PMut and SIFT BLink (TLE2)." (PMID 18688287, 2007).
cancer (continued). "Analysis of the EGFR gene status using a few cancer cells was not possible in just two patients (3.8%), owing to insufficient amounts of the recovered DNA, but was possible in the remaining 50 patients (96.2%)." (PMID 17047654, 2006). "In this study, cancer cell lines showing sensitivity to gefitinib exhibited more phosphorylation of Akt and EGFR without ligand stimulationthan gefitinib-resistant cell lines (Mann-Whitney test:P = 0.0016, P = 0.0274, respectively)." (PMID 17150102, 2006). "In conclusion, CRC does not invariably overexpress EGFr and, most importantly, the EGFr content is frequently lower but more activated in cancer tissue than in paired normal mucosa." (PMID 17088913, 2006). "EGFR signalling activates STAT proteins in fibroblasts and a variety of carcinoma cells." (PMID 16804520, 2006). "Of these, the epidermal growth factor receptor (EGFR) has been a molecular target of considerable interest and investigation, and there has been a tremendous surge of interest in pursuing targeted therapy of cancers via inhibition of the EGFR." (PMID 16219105, 2005). "EGFr concentrations were directly correlated with steroid receptors in non-malignant tissue, whereas in cancer an inverse correlation between EGFr and steroid receptors was found." (PMID 8427782, 1993). "In addition, followed by EGFR-TKI therapy, the lesions of NSCLC patients in the effective group were significantly reduced, the growth and metastasis of malignant tumors were inhibited, and the relative expression of serum miR-183 might be affected." (PMID 41601823, 2026). "Interestingly, among several well‐established CRL5 substrates that were examined, including integrin β1, p‐SRC (Y416), ATM, RPB1, EGFR, DEPTOR, and NOXA, only integrin β1 consistently accumulated across all cancer cell lines upon APC11 knockdown using two independent siRNAs targeting APC11." (PMID 41159544, 2026). "Our study found that the elevated MSLN in hepatic metastatic TNBC could activate the EGFR as well as downstream ERK1/2 signaling pathways, thereby promoting the ability of cancer cells to survive and proliferate in the liver, and further contributing to the formation of hepatic metastases." (PMID 41513618, 2026). "These molecules exert their activity through multiple mechanisms, including the inhibition of cancer cell proliferation, induction of apoptosis, regulation of the cell cycle, and modulation of major oncogenic signaling pathways such as PI3K/AKT, MAPK, NF-κB, and EGFR." (PMID 42193064, 2026). "Moreover, we identified specific NP formulations that achieved significant EGFR depletion without compromising cell viability or triggering nonspecific uptake, highlighting their potential for targeted protein degradation in cancer therapy." (PMID 41334459, 2026). "Furthermore, emerging CSRs (EGFR, DLL3, and keratin 1) that may support next-generation TDD platforms for cancer treatment are also highlighted." (PMID 41900872, 2026). "The findings of this study, specifically, the enrichment of PI3K-Akt, EGFR, MAPK, AMPK and ERK signalling in the NTRK1/2/3-high CRC subsets, are in consonance with the established signalling relationships of NTRK1/2/3 expression with cancer signalling pathways." (PMID 41155675, 2025). "Conversely, given that p66Shc is absent in certain cancers, its expression could serve as a prognostic marker for sensitivity to EGFR- or MEK-targeted therapies." (PMID 40593476, 2025). "Moreover, TMEM43 was identified to activate the nuclear factor kappa B (NF-kB) pathway through epidermal growth factor receptor (EGFR) signaling or stabilize pre-MRNA processing factor 3 (PRPF3), thus promoting cancer cell proliferation, survival, and migration." (PMID 40725103, 2025).
cancer (continued). "In cancer cell lines, studies have demonstrated that genetic or pharmacological inhibition of MYC in MCF10A basal breast cells results in increased sensitivity to TGFB-stimulated invasion and metastasis, and signaling via Smad3 and ERK/Sp1 mediate TGFB-induced EGFR upregulation." (PMID 41373732, 2025). "In cancers where Cav1 is downregulated, restoring its expression could increase sensitivity to chemotherapy and radiation therapy, inhibit pro-survival pathways (e.g., PI3K/AKT), and improve the efficacy of targeted therapies like EGFR inhibitors." (PMID 40963741, 2025). "In certain cases, cancer cells may constitutively express PD-L1 as a result of the oncogenic activation of signaling pathways, such as those regulated by rat sarcoma (RAS), epidermal growth factor receptor (EGFR), and mitogen-activated protein kinases (MAPK), among others." (PMID 40427133, 2025). "Genetic alterations in key components of these pathways, such as EGFR, BRAF, KRAS, PIK3CA, and PTEN, have been well-documented in NSCLC, and our study suggests that CKS1B may play a role in modulating these alterations to drive cancer progression." (PMID 40165937, 2025). "Efficacy of EGFR tyrosine kinase inhibitors in EGFR-mutant cancers, regardless of histology." (PMID 40364160, 2025). "Both Mel-AF and Mel-AM could also inhibit cancer cell migration and invasion abilities; however, they did not impact EGFR expression." (PMID 40141140, 2025). "The targeted cancer therapies for HCC usually employ receptors like asialoglycoprotein receptor (ASGPR), glycyrrhetinic acid receptor, transferrin receptor, somatostatin receptor, folate receptor, retinoic acid receptors or epidermal growth factor receptor etc. to deliver drugs to liver tumors." (PMID 38990437, 2025). "Ang II stimulates vascular endothelial growth factor A (VEGF-A) expression through the epidermal growth factor receptor (EGFR), mitogen-activated protein kinase (MAPK), extracellular signal-regulated kinase (ERK1/2), and PI3K/AKT pathways, facilitating neovascularization in various cancers." (PMID 40722848, 2025). "It has also been reported that a further derivative of the EGFR allosteric inhibitor JBJ0412502 is the EGFR targeting PROTAC, selectively degrades EGFRL858R/T790M and works in conjunction with osimertinib to reduce the proliferation of cancer cells in Ba/F3 cells." (PMID 39898116, 2025). "Notably, EGFR is a well-known oncogene and a promising therapeutic target in multiple cancers, while ITGAV has recently been identified as a critical contributor to cancer metastasis." (PMID 40133476, 2025). "For example, a bispecific antibody (BsAb) that simultaneously targets both EGFR and programmed cell death protein 1 (PD1), a protein that is involved in immune checkpoint blockade, has been investigated as a novel and promising strategy to effectively treat cancers." (PMID 39940134, 2025). "EGFR-mediated MAPK and PI3K pathways are still activated after chemotherapy because the α α-subunit of glycoprotein hormones (CGA) of N-glycosylated glycoprotein hormones binds to EGFR and activates EGFR signaling, promoting the proliferation and development of cancer cells." (PMID 40296904, 2025). "Moreover, in HNSCC, IFIT3 regulates EMT and cancer stem cells by targeting PD-L1 through the PI3K/AKT pathway and may participate in responses of HNSCC cells to EGFR/ERBB inhibition." (PMID 40564154, 2025). "Specifically, the active constituents were found to inhibit cancer cell growth and metastasis by affecting mitochondrial function, regulating the expression of apoptosis-related proteins, and interfering with cell signaling pathways such as PI3K/AKT, AMPK, MAPK, and EGFR." (PMID 40620671, 2025).